CD24 (CD24 molecule)
Diseases named in the same sentence as CD24 in open-access papers (continued):
Sharing a sentence is not in itself a finding about the gene and the disease.
melanoma (continued). "Finally, we were able to show that this EPO-R+/CD24+/ErbB4+ subpopulation of melanoma cells co-expresses the putative melanoma stem cell antigen PD1 as well as the NGF-R (CD271)." (PMID 24489649, 2014). "Another marker that was found to be expressed differentially on melanoma cells was CD24." (PMID 24489649, 2014). "In humans, primary melanomas have been shown to express CD24 which, together with our data, is consistent with the increasing evidence that solid cancers including melanomas can acquire early in their evolution genomic alterations predicting significant metastatic potential." (PMID 23166783, 2012). "Interestingly, B16-F1 and B16-F10 cells induced expression of CD133, ABCB5, CD44 and CD24, which are expressed in mouse melanoma CSC-like cells during tumorigenesis, and ectopic generation of GDF3 increased the CD24 expression." (PMID 20950440, 2010). "Finally, our results support the view that GDF3 has the ability to induce progression of CD24-inducible melanoma in mice." (PMID 20950440, 2010). "Nevertheless, the enhanced sphere formation, lineage plasticity, migratory ability and drug resistance of the CD24+CD271+ sub-population may signal a contextual requirement for these stem cells when melanomas face challenging environments both clinically and in experimental systems." (PMID 40754577, 2025). "We next investigated whether the presence of CD24+ and CD24+CD271+ sub-populations led to enhanced overall survival of the CHL-1 cell line when treated with melanoma therapeutic compounds, by comparing to the A375M cell line which contains a CD271+ sub-population but does not contain CD24+ cells." (PMID 40754577, 2025). "Furthermore, CD44+/CD24+ melanoma cells have been shown to have greater tumor-forming potential in vivo than CD44+/CD24–, suggesting that the increased malignant potential might be attributable to CD24 expression." (PMID 36013184, 2022). "Besides SOX2, GDF3 has been shown to stimulate CD24 expression in melanoma cells." (PMID 34293822, 2022). "In melanoma, SOX2 mediates the upregulation of CD24, which promotes the adaptability and resistance of melanoma cells to B-Raf proto-oncogene (BRAF) inhibitor targeted therapy." (PMID 40486886, 2025). "We performed QPCR analysis on FACS sorted CD24+ and CD24− sub-populations from CHL-1, for markers of the two recognised melanoma phenotypic states—melanocytic (proliferative) and neural crest-like (invasive)." (PMID 40754577, 2025). "The CD24+ and hybrid CD24+CD271+ melanoma stem cells are resistant to targeted melanoma therapeutic agents and are present in a subset of human melanomas." (PMID 40754577, 2025). "CD24+CD271- and CD24+CD271+ stem cell sub-populations were observed in 10% of human melanomas, mainly at the invasive front." (PMID 40754577, 2025). "Herein, we characterize cells expressing MIC markers (CD20, CD24, CD133, Sca-1, ABCB1, ABCB5, ALDHhigh) in the B16-F10 murine melanoma cell line." (PMID 35408953, 2022). "A study showed that treatment of melanoma cells with BRAFi induces STAT3-dependent expression of SOX2, which, together with CD24, contributes to create an autoregulatory loop that sustains adaptive resistance to BRAF-targeted therapy." (PMID 35944584, 2022). "B16-F10 melanoma cells with expression of CD133, CD44, and CD24 generated the fastest tumor formation compared to cells with other phenotype, despite that they were implanted in five times smaller density." (PMID 33424978, 2020). "Among these genes, we confirmed up-regulation of integrin α3 (ITGα3), CD24 and NCAM1 (CD56) at the protein level, which have been previously connected to increased aggressiveness of melanoma cells." (PMID 28199980, 2017). "To further prove the potential of ABCB5 as a CSC marker in murine melanoma cells, we sorted B16F10 (CD44+CD133+CD24+) by FACSAriaTM III which have been proved to have biological characteristics of CSC." (PMID 26910836, 2016).
melanoma (continued). "Putative CSCs have been isolated from many tumour types including leukaemia, melanoma, and various carcinomas using markers such as CD133, CD24, CD44, and ALDH1." (PMID 26606927, 2015). "We also found that in most patients, distinct subfractions of melanoma cells co-express EPO-R, CD24, and ErbB4, and that EPO-R expression overlaps with NGF-R expression." (PMID 24489649, 2014). "Melanoma cells derived from the primary and secondary recipients were found to express the same phenotype when compared to the initial melanoma sample, including the EPO-R as well as ErbB4 and CD24, although expression of NGF-R was very low." (PMID 24489649, 2014). "In the present study, two markers that were reproducibly detected in a distinct subpopulation of up to 40% of all melanoma cells were EPO-R and CD24." (PMID 24489649, 2014). "Mouse melanoma CSC-like cells have a high degree of tumorigenicity and express CD133, CD44, and CD24." (PMID 20950440, 2010). "We examined the expression of CD133, CD44, CD24, and ABCB5 during tumorigenesis of B16 melanoma cells transfected with empty or GDF3-expressing vectors." (PMID 20950440, 2010). "We find that primary basal cell carcinomas, squamous cell carcinomas and thin melanomas express dramatically higher levels of many genes, including SPRR1A/B, KRT16/17, CD24, LOR, GATA3, MUC15, and TMPRSS4, than metastatic melanoma." (PMID 18442402, 2008). "Interestingly, only about 4–6% of melanoma cells such as B16-F10 and YUMM5.2, showed positivity for CD24, which was found to be exclusively restricted to the FSClow and SSChigh subpopulations." (PMID 39136818, 2025). "Unlike the CD271+ sub-population, the CD24+CD271+ and CD24+ sub-populations only occurred in 1 out of 4 established melanoma cell lines and 3 out of 31 melanoma tumour specimens." (PMID 40754577, 2025). "Notch signalling is increased in slow-cycling EMT-like and CD271+ cells in melanoma, so the reduced Notch signalling in the CD24+ cells suggests they are an alternative, non-EMT-like state." (PMID 40754577, 2025). "This enabled accurate assessment of CD24 and CD271 co-staining in each of the specimens, which was performed by both a researcher and a pathologist, guided by the matched H&E specimen to ensure that analysis of co-staining was restricted to melanoma cells." (PMID 40754577, 2025). "Sox2, CD24 and ALDH regulate self-renewal, sphere formation and tumorigenicity of melanoma CSCs." (PMID 40754577, 2025). "The expansion of the CD24-positive subpopulation leads to an elevated YES1 phosphorylation and enhanced expression of Wnt target genes, subsequently promoting melanoma formation and metastasis compared to isogenic CD24-negative cells." (PMID 38338729, 2024). "In addition, these EPO-R+/CD24+ cells were found to co-express NGF-R CD271, a marker that has recently been reported as a potential marker of melanoma-initiating cells." (PMID 24489649, 2014). "Although distinct subpopulations were also detectable using surface marker antigens, especially an EPO-R+/CD24+ subpopulation, no marker combination was found to be indicative of distinct functional properties or a particular melanoma-initiating potential." (PMID 24489649, 2014). "In most donors, subpopulations of melanoma cells also expressed the EPO-R, CD24, and ErbB4." (PMID 24489649, 2014). "The existence of melanoma-initiating cells has only been recently proposed, with the description of a subpopulation of melanoma cells expressing markers such as CD20, CD133, CD24, CD271, or the ABC transporter (ATP-binding cassette) involved in drug efflux (ABCB5), ALDH1A." (PMID 24416617, 2013). "Mouse melanoma B16-F10 cells also contain CSC-like cells, which express CD133, CD44, and CD24." (PMID 20950440, 2010). "However, the expression of CD24, CD44 and CD133 (or ABCB5) in melanoma B16 cells implies that CSC-like cells emerge during tumorigenesis." (PMID 20950440, 2010).
melanoma (continued). "CD24, a small, heavily glycosylated glycosylphosphatidylinositol (GPI)-anchored surface protein, sits at the intersection of these processes and is emerging as a context-dependent biomarker and potential mediator of aggressive, therapy-resistant melanoma states." (PMID 42126185, 2026). "Here we report our observation that the cell surface expression of CD24 is preferentially enriched in a non-adherent FSClowSSChigh melanoma subpopulation, which is generally considered a non-viable population in cultivated melanoma cell lines." (PMID 39136818, 2025). "For example, early-stage melanomas often express high levels of the immune modulator CD24 and the transcription factor GATA3, whereas progressed melanomas exhibit upregulation of the melanoma antigen family A (MAGE) antigens of unknown function, and cell cycle regulators such as CDK2." (PMID 19949544, 2009). "To determine whether LCs respond to melanoma growth in the epidermis, we established a clinically relevant syngeneicinjectable murine melanoma model using the YUMM1.7(BrafV600E/WTCdkn2a−/− Pten−/−) cell line and measured the frequency of epidermal LCs [CD11b+MHCII+CD24+EpCam+ cells; fig." (PMID 37043573, 2023). "Therefore, we focussed on CD24 alongside CD271 for further investigations in the CHL-1 cell line in order to determine whether this cell line contains a CSC sub-population that is absent from the other melanoma cell lines." (PMID 40754577, 2025). "The lack of CD24+CD271- and CD24+CD271+ stem cells in the majority of human melanoma specimens led us to conclude that they may be dispensable for melanoma progression." (PMID 40754577, 2025). "Specifically, ITGα3 is expressed by melanoma cells with a highly invasive potential, CD24 is considered a negative prognostic factor for patients with cutaneous melanoma, while CD56 is a neural marker, which can be expressed by melanomas with desmoplastic and spindle cell differentiation." (PMID 28199980, 2017). "However, the EPO-R-negative subpopulation was also found to contain melanoma-initiating cells, suggesting that EPO-R/CD24-expression is not indicative of a particular (specific) melanoma-initiating (melanoma stem cell) potential." (PMID 24489649, 2014). "Therefore, in melanoma, there may be a parallel process where Dasatinib removes CD271+ EMT-like neural crest-like cells whilst simultaneously selecting for CD24+ non-EMT-like neural crest-like cells." (PMID 40754577, 2025).
COVID-19 (45 papers, 2021 to 2025). A disease caused by infection with severe acute respiratory syndrome coronavirus 2. "This is the underlying rational for new drug developments such as EXO-CD24 (N. Arber, Israel) or Merck’s CD24-Fc to dampen overshooting immune reactions as observed during the COVID-19-related cytokine storm." (PMID 34360811, 2021). "In recent studies, CD24 has attracted attention as a promising strategy for treating COVID-19 due to its known anti-inflammatory action, especially soluble CD24 may reduce COVID-19-associated systemic immunopathology." (PMID 37919766, 2023). "NCT04902183 is a phase 2 trial that looked at HEK-293-derived EVs overexpressing CD24 in moderate-to-severe COVID-19 patients." (PMID 40430932, 2025). "In hospitalized COVID-19 patients who needs oxygen support, CD24-Fc is well tolerated and the treatment significantly accelerates clinical improvement and systematically repress inflammatory response in patients." (PMID 40779581, 2025). "Another clinical trial in Israel (NCT04747574) administered CD24-loaded EVs derived from HEK293 cells to COVID-19 patients, with encouraging outcomes." (PMID 38609955, 2024). "Exosomes enriched with an immune checkpoint modulator called CD24 (EXO-CD24) deliver the protein CD24 into the body through vesicular exosomes to regulate cytokine storms and combat COVID-19." (PMID 38378653, 2024). "More critically, since the outbreak of COVID-19, CD24-Fc have also been identified to treat novel coronavirus patients, for reducing the inflammatory response caused by viruses and maintaining the stability of the immune system." (PMID 37919766, 2023). "This is reinforced by the fact that MK-7110, a candidate drug targeting CD24, is currently being tested for COVID-19 patients in a phase III clinical trial by Merck." (PMID 36851954, 2023). "It delivers the drug CD24 into the body via vesicular exosomes, which regulate cytokine storms and thus resist COVID-19." (PMID 37484024, 2023). "The discoveries on CD24-Siglec interactions propelled active translational research to treat graft-vs-host diseases, cancer, COVID-19 and metabolic disorders." (PMID 37228622, 2023). "In another clinical trial study, the safety and potential effectiveness of CD24-Exosome (EXO-CD24), a protein with anti-inflammatory properties, were evaluated in two tertiary care hospitals in Athens, Greece, in patients hospitalized with severe COVID-19." (PMID 37475025, 2023). "This was consistent with the results of a recently published study that found increased expression of CD24 to be strongly correlated with COVID-19 status and severity and involved in neutrophil degranulation." (PMID 36851954, 2023). "Although the trials targeting CD24 have been clinically evaluated in COVID-19 patients with promising preliminary outcomes, their development will require additional investigation in future." (PMID 37919766, 2023). "The main objective of the current narrative review is to describe the physiology of CD24 and EVs and to present data on their potential role, both independently and combined, in COVID-19 therapeutics." (PMID 36294907, 2022). "Exosomes overexpressing CD24 from engineered cell line has already been used to prevent the COVID-19." (PMID 35813192, 2022). "Exosomes are engineered to overexpress CD24, an endogenous immunomodulator of the immune system, aiming to target the cytokine storm in the lungs of COVID-19 patients." (PMID 35891282, 2022). "During the pandemic, CD24 has gained attention as a possible treatment for COVID-19 due to its known anti-inflammatory action." (PMID 36294907, 2022). "In the current review, we describe the physiology of CD24 and EVs and try to elucidate their role, both independently and as a combination, in COVID-19 therapeutics." (PMID 36294907, 2022). "Pilot studies depict significant amelioration of the inflammatory milieu in the setting of mild to moderate COVID-19 treated by CD24 administration." (PMID 36294907, 2022).
COVID-19 (continued). "Patients with moderate COVID-19 expressed significantly higher levels of CD66b, CD11b, CD11a, and CD24 compared to patients with severe COVID-19." (PMID 34548411, 2021). "There are ongoing therapeutic phase II/III studies in severe COVID-19 patients based on recombinant CD24 molecules administered systemically or via inhalation." (PMID 33975537, 2021). "Furthermore, emerging research has revealed the key role of CD24 in various health conditions, including autoimmune diseases, graft-vs.-host disease, and COVID-19." (PMID 40486886, 2025). "Herein, we spotted CD58, a nonclassical monocyte, such as CD274 (PD-L1) known inhibitor of T-cell activation along with Arginase 1 highly expressed in neutrophils in COVID-19 patients or CD24 involved in neutrophil degranulation with an increased expression of neutrophil function." (PMID 36806094, 2023). "In addition, sera of mild COVID-19 patients contained more HLA-ABC + EVs than healthy controls and more CD24 + EVs than that observed in severe COVID-19 patients." (PMID 37817137, 2023). "Recently, the anti-inflammatory effects of CD24 activation have also been explored as a strategy to counteract immune-related adverse events graft-versus-host disease, and sever inflammations, and recently in the COVID-19 treatment." (PMID 37359556, 2023). "Consequently, exosomes derived from CD24-overexpressing 293T cells, T-RexTM (EXO-CD24), are developed for the treatment of COVID-19 cytokine storms with the format of inhalation." (PMID 36232549, 2022). "Thus, Siglec-9is a therapeutic target to inhibit potentially fatal hyperinflammationassociated with COVID-19 in an analogous fashion to the highly effectivetherapeutics currently aimed at the Siglec-10/CD24 interaction." (PMID 34056095, 2021). "When separating the three datasets, we could see that three months after the acute infection, the long COVID-19 patients sample had a prominent immature neutrophil population in their PBMCs, which had expressed markers such as CD24 and DEFA3, and this population had almost diminished after 2 years." (PMID 38248331, 2024). "Importantly, CD24Fc and CD24 exosomes may act through Siglec stimulation to protect against severe COVID-19." (PMID 37919766, 2023). "The inhalation form of exosomes overexpressing CD24 (EXO-CD24), is a well-tolerated novel and effective treatment option in patients with mild-moderate COVID-19 related ARDS." (PMID 38561798, 2024). "Among differentially expressed proteins, CD24, CD146 and CD326 show remarkably higher expressions in EPs from COVID-19 patients." (PMID 37207201, 2023). "The mRNA expression levels of CD24 and CFS1R were also used to evaluate their correlation with the COVID-19 patients' ventilatory status." (PMID 36851954, 2023). "Of interest, among the significant plasma cytokines detected in COVID-19 patients, IL-8 showed a positive correlation with CD19, CD69 and ROR1 whereas IL-6 positively correlates with MFI CD24." (PMID 37207201, 2023). "FACS confirmed the reported increase in immature CD15++/CD24++ neutrophils and the reduction of CD14++/CD16dim classic monocytes during severe COVID-19 (WHO grade > 4), indicative of myeloid exhaustion." (PMID 35998224, 2022). "PCA analysis recapitulated these differences, highlighting CD193, CD66b, CD11a, CD24, CXCR4, and CD62L as the most affected parameters in eosinophils from COVID-19 patients." (PMID 34548411, 2021). "Subsequent studies demonstrate that sialylated CD24 (SialoCD24) is a major endogenous ligand for CD33-family of Siglecs to protect the host against inflammatory and autoimmune diseases, metabolic disorders and most notably respiratory distress in COVID-19." (PMID 37228622, 2023). "Genes associated with the immature neutrophil subset (CD24, LTF, CAMP) were up-regulated in COVID-19(+) TV skin, but not in COVID-19(+) PU or COVID-19(-) PU skin tissue." (PMID 37026002, 2023).
COVID-19 (continued). "The normalized data were used to identify whether there was any difference in the mRNA expression levels of CD24 and CFS1R between COVID-19 patients who were admitted to the ICU (n = 50) and those who were not admitted to the ICU (n = 50)." (PMID 36851954, 2023). "CD24-Fc is currently being studied as a potential therapeutic in conditions characterized by systemic inflammation, as diverse as graft-versus-host disease (GVHD), cancer, and COVID-19." (PMID 36294907, 2022). "Additionally, a recent phase III trial (NCT04317040) demonstrated that CD24-Fc effectively reduced systemic inflammation and promoted immune homeostasis in severe COVID-19 patients, without compromising the anti-viral antibody response." (PMID 40779581, 2025). "Additionally, CD24 and CSF1R may also potentially serve as novel targets for antiviral drug development, which effectively assists COVID-19 treatment." (PMID 36851954, 2023). "Indeed, expression of PIRAT in PBMC samples from control and COVID-19 patients correlated with the relative abundance of CD24+ neutrophils and classic monocytes, but not with nonclassic monocytes, in agreement with little expression of PIRAT in the latter." (PMID 35998224, 2022). "RA and COVID-19 hospitalization, severe COVID-19 have two same immune cells phenotypes (CD27 on IgD + CD24 + B cell and CD3 on CD39 + CD8 + T cell), but it does not have the same immune cells as SARS CoV-2 infection." (PMID 40495223, 2025).